TBC1D10A (TBC1 domain family member 10A)
Description:
GTPase-activating protein (GAP) specific for RAB27A and RAB35. Does not show GAP activity for RAB2A, RAB3A and RAB4A.
Synonyms: EPI64; TBC1D10; AC004997.C22.2; dJ130H16.1; dJ130H16.2
Tractability: Antibody: its Gene Ontology location is reachable by antibodies, with high confidence; the Human Protein Atlas places it where antibodies can reach. PROTAC: ubiquitination databases record sites on it; its protein half-life has been measured.
Gene: Protein-coding gene on chromosome 22 (30,291,990 to 30,326,947, reverse strand). Ensembl gene ENSG00000099992.
Subcellular location: Cell projection, microvillus
Subcellular location (Human Protein Atlas): Plasma membrane
Pathways (Reactome):
Vesicle-mediated transport: TBC/RABGAPs
Gene Ontology:
Molecular function: cadherin binding; GTPase activator activity; PDZ domain binding; protein binding
Biological process: positive regulation of proteolysis; regulation of cilium assembly; retrograde transport, endosome to Golgi
Cellular component: extracellular exosome; plasma membrane; microvillus; cytosol
Genetic constraint (gnomAD): Loss-of-function variants: 27 observed, 54.58 expected, observed/expected ratio (o/e) 0.49, 90% interval 0.36 to 0.68. The upper end of that interval is the gene's LOEUF score, 0.68, which puts it in group 2 of 6, group 1 being the genes least tolerant of losing a copy. Missense variants: 602 observed, 672.41 expected, observed/expected ratio (o/e) 0.9, 90% interval 0.84 to 0.96. Synonymous variants: 278 observed, 277.67 expected, observed/expected ratio (o/e) 1, 90% interval 0.91 to 1.11.
Homologues: Orthologues: chimpanzee TBC1D10A (100% identical), macaque TBC1D10A (98% identical), pig TBC1D10A (92% identical), dog TBC1D10A (91% identical), rat Tbc1d10a (91% identical), guinea pig TBC1D10A (91% identical), mouse Tbc1d10a (91% identical), rabbit TBC1D10A (81% identical), tropical clawed frog tbc1d10a (66% identical), zebrafish tbc1d10ab (65% identical), zebrafish tbc1d10aa (54% identical). Paralogues in human: TBC1D10B (57% identical), TBC1D10C (40% identical), TBC1D9 (25% identical), TBC1D9B (24% identical), EVI5L (24% identical), USP6NL (24% identical), EVI5 (23% identical), TBC1D8 (23% identical), TBC1D8B (23% identical), RABGAP1 (23% identical), RABGAP1L (23% identical), TBC1D4 (23% identical), and 33 more.
Diseases named in the same sentence as TBC1D10A in open-access papers:
TBC1D10A is named in the same sentence as 6 diseases in open-access papers, as found by Europe PMC text mining. Sharing a sentence is not in itself a finding about the gene and the disease. The quoted sentences say what the papers report.
breast carcinoma (1 paper, 2018). "Further investigations of common pRESs discovered that BDH1, CCDC137, and TBC1D10A transcripts contained a single non-synonymous RNA variant that was unique to breast cancer tissue compared to adjacent normal tissue; thus, further clinical validation is required." (PMID 30071094, 2018).
cancer (3 papers, 2018 to 2024). A tumor composed of atypical neoplastic, often pleomorphic cells that invade other tissues. "The expression levels of the BDH1 and TBC1D10A genes were downregulated, while the CCDC137 gene was upregulated in cancer tissue compared to adjacent normal tissue." (PMID 30071094, 2018). "Based on the pRESs, the following amino acid changes were predicted in cancer tissue compared to adjacent normal tissue: K275R in BDH1, Q288E in CCDC137, and D44H in TBC1D10A." (PMID 30071094, 2018).
TBC1D10A also shares sentences with these, for which no sentence is quoted: hepatocellular carcinoma (1 paper); melanoma (1); skin cutaneous melanoma (1); tumor (1).